HIF1A (hypoxia inducible factor 1 subunit alpha)
Diseases named in the same sentence as HIF1A in open-access papers (continued):
Sharing a sentence is not in itself a finding about the gene and the disease.
osteoarthritis (42 papers, 2005 to 2025). A noninflammatory degenerative joint disease occurring chiefly in older persons, characterized by degeneration of the articular cartilage, hypertrophy of bone at the margins and changes in the synovial membrane. "In osteoarthritis, which is primarily caused by degeneration of articular cartilage, HIF-1α is upregulated in chondrocytes and is believed to protect articular cartilage by acting anabolically on it." (PMID 39273346, 2024). "Our results showed that ucOCN inhibits chondrocyte hypertrophy and protects against osteoarthritis, primarily through the activation of the HIF-1α pathway via the GPRC6A receptor." (PMID 40765832, 2025). "DOT1L, which methylates lysine 79 of histone H3, is one of the targets of HIF-1α and contributes to the protective effects of hypoxia on osteoarthritis." (PMID 38732122, 2024). "Our results showed that these proteins were associated with some signaling pathways including “Osteoarthritis Pathway”, “Inhibition of Matrix Metalloproteases”, “STAT3 pathway”, “HIF1α signaling”, “NRF2-mediated Oxidative Stress Response”, and others." (PMID 38890638, 2024). "In osteoarthritis, capsiate treatment is related to decreased HIF-1α expression and oxidative stress levels." (PMID 38732122, 2024). "A different research study found that has reported that the activation of lncRNA SLC2A1 declined the expression of HIF-1α to inhibit osteoarthritis." (PMID 38740637, 2024). "The DEGs in the palovarotene-treated AcanCreER;Ext1f/f chondrocytes compared to those in control AcanCreER;Ext1f/f chondrocytes were strongly linked to the upregulation of the hypoxia-inducible factor 1a (HIF1a) signaling and osteoarthritis pathways." (PMID 39062860, 2024). "Ingenuity® Pathway Analysis (IPA) of DGEs from RES or POG-treated osteoblasts revealed significant downregulation of the apoptosis, osteoarthritis and HIF1α canonical pathways, and a significant reduction in Rankl mRNA expression." (PMID 37513651, 2023). "Our findings indicated that CAT inhibited HIF‐1a expression and reduced ferroptosis‐dependent osteoarthritis progression by activating SLC2A1." (PMID 36890785, 2023). "To our knowledge, we are the first to report that the protective effect of CAT against osteoarthritis is mediated by the inhibition of HIF‐1 α and activation of SLC2A1, thereby inhibiting ferroptosis progression." (PMID 36890785, 2023). "Our findings indicated that CAT inhibited HIF‐1a expression and reduced ferroptosis‐relative osteoarthritis progression by activating SLC2A1." (PMID 36890785, 2023). "In our study, we also found a significant increase in HIF‐1 α in the cartilage of mice with osteoarthritis, and the expression of HIF‐1 α was significantly inhibited by the use of ferroptosis inhibitors." (PMID 36890785, 2023). "Ingenuity Pathway Analysis (IPA) analysis showed Osteoarthritis, HIF1α, circadian rhythm and PI3K/AKT pathways as significantly regulated by both osmotic stress and treadmill running." (PMID 37963878, 2023). "In this regard, HIF1α Signaling and the Osteoarthritis Pathway were highly and rapidly induced, demonstrating that hypoxia is a critical factor for osteocyte function." (PMID 36650133, 2023). "We used “osteoarthritis,” “HIF-1α,” “hypoxia,” “mechanism,” “inflammation,” and “treatment” as keywords." (PMID 35865944, 2022). "In this review, we summarize the mechanism of hypoxia in the pathogenic mechanisms of osteoarthritis, and focus on a series of therapeutic treatments targeting HIF-1α for osteoarthritis." (PMID 35865944, 2022). "Studies have found that HIF-1α levels are significantly related to the severity and progression of osteoarthritis." (PMID 36503684, 2022). "For osteoarthritis, increasing the accumulation and activity of HIF-1α to increase cartilage stability and inhibiting the activity of HIF-2α to reduce ECM degradation are promising therapeutic approaches." (PMID 36503684, 2022).
osteoarthritis (continued). "In conclusion, electroacupuncture for osteoarthritis is accomplished by upregulating the expression of HIF-1α, Sox9, and ACAN and downregulating the expression of MMP13 and ADAMTS5." (PMID 34760015, 2021). "The present study demonstrated that HIF-1α, highly expressed in normal articular cartilage, exerts protective effects against cartilage degeneration and osteoarthritis development." (PMID 32214220, 2020). "Treatment of desferrioxamine (DFO) treatment, a known HIF-1α activator, to osteoarthritis chondrocytes significantly reduced lipid accumulation." (PMID 29050208, 2017). "Our data indicate that deregulation of a HIF-1a:CRAT:miR-144-3p axis impairs peroxisomal function during the pathogenesis of osteoarthritis." (PMID 29050208, 2017). "In conclusion, DHJST exerts significant therapeutic effect on osteoarthritis rabbits, and mechanisms are associated with inhibition of VEGF and HIF-1α expression." (PMID 21792361, 2011). "The present study investigated the effects of inhibiting or stabilizing hypoxia-inducible factor (HIF)-1α by 2-methoxyestradiol or dimethyloxaloylglycine on the progression of osteoarthritis in murine knee joints." (PMID 18789153, 2008). "Mechanistically, L. sakei LB-P12 may improve osteoarthritis through regulation of the NF-κB/HIF-2α/HIF-1α signaling pathway in chondrocytes and macrophages." (PMID 40329628, 2025). "Also, we found that CAT inhibited HIF‐1a expression and reduced ferroptosis‐dependent osteoarthritis progression by activating SLC2A1." (PMID 36890785, 2023). "Thus, HIF-1α is likely to be a crucial therapeutic target for osteoarthritis via regulating chondrocyte inflammation and metabolism." (PMID 35865944, 2022). "Further clarification of the regulatory mechanisms of HIF-1α in osteoarthritis may provide more useful clues to developing novel osteoarthritis treatment strategies." (PMID 35865944, 2022). "Moreover, several researches in osteoarthritis indicated that GSDMD-mediated FLSs pyroptosis participates in HIF-1α-induced synovial fibrosis in knee osteoarthritis." (PMID 35237610, 2021). "We examined HIF-1α protein expression and the hypoxic condition during mouse osteoarthritis (OA) development using state of the art hypoxic probes and found that its expression decreased as OA progressed, coinciding with the change in hypoxic conditions in articular cartilage." (PMID 32214220, 2020). "HIF1A regulates oxygen homeostasis, glucose transport and generation of anaerobic energy in joints and chondrocytes, and may play an important role in the osteoarthritis metabolism." (PMID 32493207, 2020). "Nevertheless, Hif-1α appeared to be clinically important in the development of osteoarthritis." (PMID 28349987, 2017). "In addition, low oxygen tensions and hypoxia-inducible factor-1alpha (HIF-1α) are important factors in articular chondrocyte behaviour during cartilage homeostasis and osteoarthritis." (PMID 28426699, 2017). "According to this paradigm, a stress-induced increase in the activity of HIF-2α will overshadow the beneficial effects of the closely related HIF-1α, then push the chondrocytes in the joint toward a more differentiated state known as hypertrophy, which then drives osteoarthritis changes." (PMID 25617057, 2015). "Furthermore, positive correlation of plasma lactate, cartilage HIF1α and cytokine levels with the body mass index was observed in subjects with osteoarthritis." (PMID 26271607, 2015). "To investigate the hypothesis that therapeutic stabilization of HIF-1α in articular chondrocytes would prevent the progression of osteoarthritis in STR/ORT mice, we injected DMOG into the left knee joints once a week during the entire period of 12 weeks." (PMID 18789153, 2008). "We speculated that HIF-1α may have an important role in chondrocyte viability as a cell survival factor during the progression of osteoarthritis (OA)." (PMID 15987493, 2005). "In summary, HIF-1α may become a potential target for treating osteoarthritis." (PMID 32587244, 2020).
osteoarthritis (continued). "Therefore, these important findings revealed that DMOG-induced up-expression of HIF-1α could alleviate osteoarthritis via activation of autophagy." (PMID 32587244, 2020). "For example, capsiate inhibited the expression of HIF-1α by activating SLC2A1, thereby reducing the progression of ferroptosis-related osteoarthritis." (PMID 40809843, 2025). "Due to lipid peroxidation being an important part of ferroptosis, we used primary chondrocytes from osteoarthritis patients to analyze the role of SLC2A1 and HIF‐1α in the progression of osteoarthritis." (PMID 36890785, 2023). "The precise role of HIF-1α in articular cartilage development and the clinical significance of aberrant PHD2/HIF-1α signaling in osteoarthritis development needs to be investigated further." (PMID 28349987, 2017). "In addition, we further investigated the possibile mechanism of HIF‐1a expression and SLC2A1 which effect by gut microbiota metabolite CAT and provide a theoretical basis for CAT treatment of osteoarthritis." (PMID 36890785, 2023). "Previous studies failed to elaborate the relationship between HIF-1α and mitophagy in osteoarthritis." (PMID 32587244, 2020). "Simultaneously, GABA, LysoPA(18:1(9Z)/0:0) and L-Targinine, the unique metabolites of RA EP, might participate in neuroinflammation signaling pathway, osteoarthritis pathway, glucocorticoid receptor signaling, ILK signaling, IL-17 signaling and HIF1α signaling." (PMID 35706052, 2022). "However, neither HIF-1α nor HIF-2α was detected in human osteoarthritis (n = 10), psoriatic arthritis (n = 2), or gouty arthritis (n = 2) synovium." (PMID 24914685, 2014). "However, this hypothesis contradicted research showing that stabilization of HIF-1α by dimethyloxaloylglycine did not prevent osteoarthritis development in the knee joints of STR/ORT mice." (PMID 28349987, 2017). "Based on these data, one would expect a negative effect of HIF-1α on the maintainence of articular cartilage, and higher levels of HIF-1α could contribute to the pathogenesis of osteoarthritis." (PMID 28349987, 2017).
sarcoma (42 papers, 2012 to 2025). A usually aggressive malignant neoplasm of the soft tissue or bone. "Loss or enhanced expression of PLOD2 abolishes or restores, respectively, the metastatic potential of HIF1α-deficient tumors and human sarcomas typically display high HIF1α and PLOD2 expression in metastatic primary lesions." (PMID 36232732, 2022). "Loss or overexpression of PLOD2 abrogates or restores, respectively, the metastatic potential of HIF1α-deficient tumors and human sarcomas show elevated HIF1α and PLOD2 expression in metastatic primary lesions." (PMID 34294128, 2021). "YB-1, an enhancer of HIF1α translation, is overexpressed in high-risk human sarcomas and promotes EMT and metastasis." (PMID 34294128, 2021). "For instance, in HIF-1α-deficient human sarcoma, the expression of ectopic PLOD2 restored the potential of migration and metastasis, while inhibiting the activity of PLOD2 resulted in decreased tumor metastasis." (PMID 34944486, 2021). "HIF1a expression and hypoxia are associated with poor survival of sarcoma patients." (PMID 34294128, 2021). "Notably, in sarcoma patients, increased HIF-1α and CXCR4 expression are associated with advanced disease." (PMID 33322371, 2020). "Therefore, we performed the meta-analysis to derive an overall pooled estimation of the association between HIF-1α expression and outcomes of sarcoma patients." (PMID 27606158, 2016). "This analysis led to the underlying hypothesis for our study: VEGF-A and HIF-1α play critical and interdependent roles in regulating sarcoma progression." (PMID 22684860, 2013). "Literature reports that YB-1 is a crucial mediator of metastasis in sarcomas it promotes EMT by translationally upregulating factors like HIF-1α." (PMID 41174561, 2025). "El-Naggar and colleagues found that YB-1 is a key regulator of hypoxia-inducible factor 1α (HIF1α) expression in sarcoma cells." (PMID 39497723, 2024). "Another recent study showed that, among other factors, ADC skewness was associated with the expression of hypoxia-inducible factor-1 alpha (HIF-1α), a key regulator of oxygen homeostasis in sarcoma." (PMID 39594807, 2024). "YBX1 was previously identified as a critical regulator of HIF1A expression in sarcoma leading to enhanced metastatic capacity in vivo." (PMID 36936386, 2023). "In sarcoma, increased expression of PLOD2 is associated with a more metastatic phenotype, and loss of HIF-1α and HIF-1α-dependent PLOD2 expression disrupts cell migration and pulmonary metastasis." (PMID 37490147, 2023). "YBX1 protein was shown to be a critical regulator of HIF1α expression in sarcoma cells; however, less is known about the role of this protein in MSCs." (PMID 35163348, 2022). "In this context, it is interesting to note that we have recently found that HIF1α induction in human sarcoma cells is mediated by direct binding of YB-1 to the 5′-UTR of HIF1A transcripts to enhance their translation." (PMID 34294889, 2022). "Overexpression of HIF1α has been shown to enhance the metastatic potential of sarcomas, including EwS." (PMID 35705030, 2022). "Recently, YBX1 activates HIF-1α at the translation level by binding to the IRES sequences of the HIF-1α mRNA 5’UTR region to promote sarcoma metastasis." (PMID 31291975, 2019). "YB-1 is a multifunctional nucleic acid-binding protein that can directly bind to and activate translation of HIF1α mRNA to promote sarcoma cell invasion and enhanced metastatic capacity in vivo." (PMID 29529249, 2018). "In the current meta-analysis, we combined 16 studies with 942 sarcoma patients comparing the outcomes of metastasis and survival according to the level of HIF-1α expression." (PMID 27606158, 2016). "In one report, high expression of HIF1α mRNA in certain sarcomas was correlated with a significantly more favorable prognosis." (PMID 24216979, 2013). "Increased levels of hypoxia and hypoxia-inducible factor 1α (HIF-1α) in human sarcomas correlate with tumor progression and radiation resistance." (PMID 22684860, 2013).
sarcoma (continued). "One mechanism by which VEGF inhibition and HIF-1α inhibition synergistically inhibit sarcoma progression is via the targeting of the tumor endothelium." (PMID 22684860, 2013). "Dox is the most commonly used chemotherapeutic agent for soft tissue sarcomas, and thus, the use of this agent to block HIF-1α induction of target genes in sarcomas makes therapeutic sense." (PMID 22684860, 2013). "We found that four different sarcoma cells lines upregulate HIF-1α and specific HIF-1α target genes under hypoxic conditions." (PMID 22684860, 2013). "HT1080 sarcoma xenografts had increased hypoxia and/or HIF-1α activity with increasing tumor size and with anti-VEGF receptor antibody (DC101) treatment." (PMID 22684860, 2013). "To determine the role of HIF-1α in sarcoma cell proliferation and migration in vitro and tumor growth in vivo, we used shRNA knockdown of HIF-1α in HT1080 sarcoma cells that showed strong upregulation of HIF-1α in response to 0.5% hypoxia." (PMID 22684860, 2013). "In conclusion, sarcomas are a heterogeneous group of solid tumors in which hypoxia and HIF-1α activity play varying roles." (PMID 22684860, 2013). "The mechanisms underpinning HIF1α-mediated chemoresistance need to be better studied in the heterogenous group of sarcomas that exhibit resistance to therapy." (PMID 24216979, 2013). "Moreover, downregulation of HIF-1α sensitizes sarcomas cells in vivo to radiation and decreases their clonogenic potential." (PMID 37296922, 2023). "Similarly, YB-1 enhances HIF1α protein expression by directly binding to HIF1α mRNA to activate HIF1α translation in sarcoma cells." (PMID 35406781, 2022). "Additionally, translational regulation of hypoxia-inducing factor 1α (HIF1α) by YBX1 promoted sarcoma metastasis." (PMID 34440660, 2021). "Additionally, hypoxia-inducible factor 1-alpha (HIF-1α) increases CXCR4 expression on sarcoma cells, contributing to metastasis development." (PMID 33322371, 2020). "Translation and synthesis of NRF2, as well as of other known YB‐1 targets, G3BP1 and HIF1α, were blocked by MS‐275 in sarcoma cells, due to enhanced acetylation of lysine 81 within the YB‐1 RNA‐binding domain and consequent loss of YB‐1 translational activation of these stress factors." (PMID 31668005, 2019). "YBX1 was reported could interact with HIF-1α 5’UTR to promote HIF-1α translation in sarcoma, we speculated that YBX1 may play as a cofactor of PTBP3 in regulating HIF-1α translation." (PMID 31291975, 2019). "Hypoxia and HIF-1α are known to play important roles in human sarcomas." (PMID 22684860, 2013). "HIF-1α, in contrast, is expressed by both endothelial cells and sarcoma cells and may have effects on both cell types." (PMID 22684860, 2013). "Hierarchical clustering analysis using expression data from >100 hypoxia-related genes on oligonucleotide microarrays of sarcomas and normal tissues identified distinctly different patterns of expression; numerous hypoxia-related genes were significantly up-regulated in sarcomas including HIF1α." (PMID 24216979, 2013). "Thus, we examined the role of hypoxia and HIF-1α in sarcoma progression as well as the combination of VEGF-A and HIF-1α inhibition in sarcomas." (PMID 22684860, 2013). "Genetic deletion of HIF-1α using shRNA or the pharmacologic blockade of HIF-1α binding to target DNA using low-dose Dox act synergistically with VEGF inhibition to suppress the growth of sarcoma xenografts." (PMID 22684860, 2013). "In conclusion, sarcomas respond to increased hypoxia by expressing HIF-1α target genes that may promote resistance to antiangiogenic and other therapies." (PMID 22684860, 2013). "A strong HIF-1α transcriptional program may be a means of resistance for some sarcomas to anti-VEGF therapy." (PMID 22684860, 2013). "Thus, we analyzed anti-VEGF treatment and HIF-1α inhibition in sarcoma cell lines in vitro as well as in a sarcoma mouse model and demonstrated the therapeutic potential of this novel strategy." (PMID 22684860, 2013).